FOXO1 (forkhead box O1)
Diseases named in the same sentence as FOXO1 in open-access papers (continued):
Sharing a sentence is not in itself a finding about the gene and the disease.
diabetes (continued). "The role of FoxO1 in metabolism has been well studied, but recently FoxO1’s potential for diabetes prevention and therapy has been debated." (PMID 37941908, 2023). "In support of these findings, Foxo1/3/4 deletion in osteoblast progenitors reverses the diabetes impact on reducing cancellous bone mass by limiting osteoclastogenesis in mice with T1DM." (PMID 37591875, 2023). "In contrast, Foxo1 ablation in Dia osteoblasts (Dia OsxcretTAFoxo1f//f), restored osteogenesis which were impaired by diabetes." (PMID 37591875, 2023). "Diabetes also enhances Foxo1 DNA binding to TNF-α and RANKL promoters and increases their expression in diabetic fracture calluses." (PMID 37591875, 2023). "Inhibition of Foxo1 and/or restoration of cilia formation has the potential to promote diabetes-impaired fracture healing." (PMID 37591875, 2023). "We report here that streptozotocin (STZ)-induced type 1 diabetes mellitus (T1DM) dramatically increased Foxo1 expression in femoral fracture calluses, which thereby caused a significant decrease in the expression of IFT80 and primary cilia number." (PMID 37591875, 2023). "Replacing both endogenous alleles of Cdk4 with Cdk4-R24C prevented diabetes in IRS2-null male mice by rescuing β cell mass, function, and differentiation and restoring cytoplasmic FOXO1 location and nuclear PDX1 abundance in β cells in vivo." (PMID 37712417, 2023). "The vast majority of experiments on the role of FOXO1 in the AGE-RAGE signaling pathway have focused on diabetes and its complications." (PMID 35154571, 2022). "It is well known that FoxO1 and/or FoxO3a participate in the regulation of various cell death seen during insulin resistance and diabetes." (PMID 36035917, 2022). "FoxO1 expression levels are increased in various tissues in diabetic mice and are involved in diabetes‐induced oxidative stress and cell apoptosis." (PMID 35842903, 2022). "In the current study, a decreasing tendency of FoxO1 was observed along with elevated Th17 cells and reduced Tregs following the progress of diabetes in db/db mice." (PMID 36463128, 2022). "Accumulating evidence has indicated that FoxO1 also contributes to the progression of diabetes‐induced organ damage." (PMID 35842903, 2022). "FoxO1 is a TGFβ-1 downstream crucial player in cardiac fibroblast conversion into cardiac myofibroblasts, which, under pathological conditions such as diabetes mellitus, synthesizes and secretes high amounts of ECM proteins." (PMID 34803741, 2021). "A number of studies have revealed that the renoprotective effect of certain drugs used to treat diabetes or some protein molecules is FoxO1-mediated." (PMID 33859563, 2021). "In line with this, in a rat model of mild diabetes, the heart of male adult offspring was found to show an increase in active FoxO1." (PMID 34803741, 2021). "In particular, further exploration of FOXO1 in immune responses under pathological conditions such as periodontitis and diabetes mellitus will be important to establish the full involvement of FOXO1." (PMID 33860060, 2021). "Patients with muscle atrophy from type 2 diabetes mellitus show increased expression of NF-κB and higher expression of the atrophy transcription factor FOXO1 in skeletal muscle." (PMID 33540675, 2021). "Strikingly, all BDC.Foxo1–/– female mice (n = 12) developed diabetes between 3 and 5 weeks of age, which was marked by islet infiltration, suggesting a prominent role for Foxo1 in T1D development." (PMID 34314385, 2021). "Male adult offspring from rats with mild diabetes show an increase in cardiac active FoxO1, together with an increase in the mRNA levels of its target genes in the heart, Mmp-2 and Ctgf, and in collagen deposition and fibrosis." (PMID 34803741, 2021). "Diabetes led to a significant increase in Foxo1 mRNA compared with NDC group in both sexes (P < 0.001)." (PMID 34848753, 2021).
diabetes (continued). "Highly functioning FoxO1 triggers hyperglycemia as well as dyslipidemia, which are the features of diabetes and diabetic problems under insulin-resistant circumstances." (PMID 33804729, 2021). "Dysfunction of the FoxO1 pathway leads to various metabolic diseases, including diabetes, obesity, nonalcoholic fatty liver disease, and atherosclerosis." (PMID 34539243, 2021). "1,25D treatment or FoxO1 knockout rescued the inhibitory effect of diabetes on osteoblastic markers to a large extent, and down‐regulated the expression of Cathepsin K gene (P <.05)." (PMID 33609082, 2021). "Studies have confirmed that FOXO1 plays a role in many diseases, such as cardiovascular diseases, diabetes, cancer, aging, and stem cell activation." (PMID 34867446, 2021). "Activation of SIRT1 led to deacetylation of FOXO1 and increased the transcriptional activity of FOXO1, ultimately enhanced the autophagy flux and protected diabetes-induced cardiac injury." (PMID 34367065, 2021). "Subsequently, we demonstrated that FoxO1 inhibition reversed the phenotypic switch of SMCs and lowered the chronic inflammatory states, thereby preventing diabetes‐driven tunica media dysfunction." (PMID 33108705, 2020). "Alterations of FoxO1 occur in the cardiovascular system in diabetes, yet the role of FoxO1 in diabetic vascular complications is poorly understood." (PMID 33108705, 2020). "BXXD protected MIN6 cells against t-BHP-induced apoptosis and improved insulin secretory function through modulation of the PI3K/AKT pathway and the downstream FOXO1, thus suggesting a novel therapeutic approach for type 2 diabetes mellitus (T2DM)." (PMID 32377518, 2020). "Recent studies show that FoxO1 promotes inflammation during diabetes by enhancing TLR4‐mediated signalling." (PMID 33108705, 2020). "Our data show that SET8 decreased and FOXO1 increased in the peripheral blood mononuclear cells of patients with diabetes and the aortic tissues of diabetic rats." (PMID 33028948, 2020). "Our in vivo study indicated that SET8 was downregulated and FOXO1 was upregulated in the peripheral blood mononuclear cells of patients with diabetes and the aortic tissues of diabetic rats." (PMID 33028948, 2020). "Dysfunction of FoxO1 pathways results in several metabolic diseases, including diabetes, obesity, non-alcoholic fatty liver disease, and atherosclerosis." (PMID 31936903, 2020). "We first investigated the expression of FoxO1 in the carotid arteries of Sprague‐Dawley (SD) rats at 8 weeks of the diabetes." (PMID 33108705, 2020). "The findings from these studies indicate that FOXO1 plays an essential role in the process of diabetes." (PMID 33028948, 2020). "Dedifferentiation of β cells in the context of diabetes has been shown to occur in vivo through genetic disruption of the key transcription factor Foxo1." (PMID 31440379, 2019). "FOXO1 regulates the expression of several genes that play roles in the development and progression of diabetes mellitus and DN." (PMID 30962862, 2019). "Tissue-specific Foxo1 overexpression in transgenic mice had a protective effect on the renal function and partially reversed tubular injuries by attenuating the diabetes-induced increase in TXNIP and decrease in the TRX levels." (PMID 30962862, 2019). "Among them, Foxo1, Myc, Yy1, and Cebpa were reported in literature to be essential TFs in regulating diabetes." (PMID 29995913, 2018). "SREBP1c and FOXO have been reported to play a role in transcriptional regulation of metabolism at high glucose levels, FOXO-1 in cardiac pathology in diabetes mellitus, PPARγ in lipid metabolism, and PPARs in cardiac dysfunction in diabetic cardiomypathy." (PMID 30385846, 2018). "Studies have revealed the involvement of FoxO1 in the development of cardiovascular diseases and diabetes." (PMID 30294283, 2018). "On the other hand, partial protection against high fat diet-induced diabetes has been shown in FOXO1 (forkhead box O-1) haploinsufficient mice." (PMID 30376839, 2018).
diabetes (continued). "Understanding the mechanism responsible for the impaired keratinocytes migration in diabetes by characterizing the excessive MMP9 expression mediated by FOXO1 will help set the basis for clinical application of a FOXO1 antagonist in treating diabetic wounds." (PMID 28874756, 2017). "Consistent with our results, it has been demonstrated that deletion of IRS1 and IRS2 genes in mice prevented activation of liver Akt-Foxo1 phosphorylation and led to the development of diabetes." (PMID 29207597, 2017). "Keratinocyte-specific deletion of Foxo1 blocked the diabetes-induced increase in MMP9 expression in vivo." (PMID 28874756, 2017). "On the contrary, maternal diabetes increased the expression of Foxo1, but this response was significantly blunted in Alx3-null embryos." (PMID 28341857, 2017). "Our results suggest that decreased hepatic H19 levels during diabetes promote FoxO1 nuclear localization and increase gluconeogenesis." (PMID 28814771, 2017). "Further, FOXO1 nuclear compartmentalization and enhancement of its transcriptional activity was observed especially during diabetes and obesity." (PMID 26956801, 2016). "In summary, this study demonstrated that, in the late stage of STZ-induced diabetes, rats displayed the inactivation of STAT3, APN deficiency, and the increase of FoxO1 and CD36 expression." (PMID 26783539, 2016). "Diabetes showed reduction of cardiac STAT3 activation (p-STAT3) and adiponectin with concomitantly increase of FoxO1 and CD36, which associated with reduced sevo-postC cardioprotection." (PMID 26783539, 2016). "In the present study, we found that, in the late stage (8 weeks of diabetes) of STZ-induced diabetes, rats displayed the inactivation of STAT3, APN deficiency, and the increase of FoxO1 and CD36 expression." (PMID 26783539, 2016). "Impaired insulin signaling in the liver leads to the failure of insulin to suppress gluconeogenesis through the FoxO1 pathway, leading to hyperglycemia and ultimately diabetes (Haas and Biddinger, 2009; Leavens and& Birnbaum, 2011)." (PMID 26067236, 2015). "Mounting evidence including the rescue of insulin sensitivity on FoxO1 haploinsufficient mice and the induction of diabetes in FoxO1 gain‐of‐function mutant mouse shed light on these pathogenetic roles of FoxO proteins." (PMID 26176567, 2015). "In vivo experiments demonstrate that diabetes enhances FOXO1 DNA binding activity and increases FOXO1 nuclear translocation in chondrocytes." (PMID 24864265, 2014). "Patients with diabetes suffer disproportionately from impaired lipid metabolism and FOXO1 controls aspects of lipid metabolism in the diabetic liver." (PMID 24864265, 2014). "Overexpression of constitutively active FOXO1 targeted to the liver and pancreatic β-cells results in diabetes arising from a combination of increased hepatic glucose production and inhibited β-cells compensatory growth due to decreased Pdx1 expression." (PMID 24864265, 2014). "Recent studies have shown that FOXO1 is an important regulator of wound healing and that diabetes influences the effect of FOXO1." (PMID 25226535, 2014). "In vivo experiments indicate that diabetes increases FOXO1 mRNA levels, DNA binding activity, and nuclear translocation mediated by TNF-α in retinal microvascular cells." (PMID 24864265, 2014). "In contrast, knockout or knockdown of hepatic FoxO1 lowers blood glucose levels and improves systemic insulin sensitivity in genetic or diet-induced diabetic mouse models." (PMID 24015318, 2013). "Our results identify CCN3, a novel transcriptional target of FoxO1 in pancreatic β-cells, as a potential target for therapeutic intervention in the treatment of diabetes." (PMID 23705021, 2013). "Taken together, our findings suggest an important role of FoxO1/3/4 in the regulation of glucose metabolism under physiological conditions and a potential implication in the pathogenesis of diabetes." (PMID 24015318, 2013).
diabetes (continued). "In vivo, FOXO1 DNA activity is increased twofold in diabetic wounds, and the increase is driven by diabetes-enhanced TNF levels." (PMID 23484152, 2013). "For example, in microvascular endothelial cells, FOXO1 is induced in vivo by diabetes-enhanced TNF-α and also induces expression of TNF-α levels in these cells." (PMID 22454632, 2012). "We previously reported that FoxO1 haploinsufficiency restored β cell mass and rescued diabetes in IRS2 knockout mice." (PMID 22384192, 2012). "It has been proposed that diabetes-enhanced activation of FOXO1 limits wound healing by enhancing fibroblast apoptosis and proliferation." (PMID 22454632, 2012). "In one study, the authors evaluated the potential of OGT derived O-β-GlcNAc modifications on FoxO1 protein in diabetes." (PMID 22489133, 2012). "One mechanism responsible for triggering apoptotic signaling is the high glucose- or diabetes-induced forkhead box protein 1 (FOXO1) activation." (PMID 22171163, 2011). "One possible pathway through which FOXO1 can be activated in response to diabetes is through the mitogen-activated protein (MAP) kinase pathway." (PMID 20300563, 2010). "In addition, AKT phosphorylation levels were increased and FOXO1 levels were reduced in knock down of hippocampal neuronal MasR in diabetic cognitive impairment mice." (PMID 40303297, 2025). "Moreover, the results suggest that hucMSC‐secreted EXOs enhance SIRT1/FoxO1/3a‐mediated mitochondrial function and ameliorate muscle atrophy in diabetes." (PMID 39871746, 2025). "This study investigated whether metformin attenuates diabetes-driven renal senescence through the modulation of the fatty acid-binding protein 4 (FABP4)/forkhead box protein O1 (FOXO1) axis and key immunometabolic enzymes." (PMID 41471323, 2025). "The idea of targeting FoxO1 originated from its studies in diabetes two decades ago." (PMID 39533662, 2025). "However, the first FoxO1 inhibition studies originated in diabetes due to its role in glucose and lipid metabolism." (PMID 39533662, 2025). "Inducing diabetes in the FoxO1-deficient littermates (Foxo1Cardiac−/−) prevented this response, with no significant increase in zDHHC4 expression or CD36 S-acylation relative to controls in response to diabetes." (PMID 40357580, 2025). "Tissue-specific overexpression of FoxO1 in transgenic mouse models conferred renal protection, partly by attenuating diabetes-induced increases in Thioredoxin Interacting Protein (TXNIP) and reducing Thioredoxin (TRX) levels, thereby partially reversing renal interstitial fibrosis and apoptosis." (PMID 39382800, 2024). "However, FoxO1, FoxO3, and FoxO4 knockout reduced the number of osteoclasts and improved bone remodeling in diabetes-induced osteoporosis." (PMID 38987770, 2024). "Thus, to investigate the effect of NGF in the Akt-FoxO1 signaling pathway in obese- and diabetes-induced muscle atrophy, the phosphorylation of Akt was evaluated in the gastrocnemius muscle tissues." (PMID 38673892, 2024). "Literature data indicate that FOXO-1 may be a new therapeutic agent in some inflammatory diseases such as diabetes, obesity, and hypertension." (PMID 38658396, 2024). "Blocking FOXO1 offers an opportunity for novel therapies for diabetes mellitus." (PMID 39329975, 2024). "However, the effects and role of FOXO1 can vary depending on the specific conditions, such as diabetes." (PMID 38658396, 2024). "Studies have shown that elevated FOXO1 expression in the liver may lead to an increase in FBG in mice, while the inhibition of FOXO1 expression in the liver may delay the progression of diabetes and fatty liver." (PMID 37601073, 2023). "Thus, our findings demonstrate that diabetes impairs fracture healing through Foxo1 mediated inhibition of ciliary IFT80 expression and primary cilia formation, resulting in impaired osteogenesis." (PMID 37591875, 2023). "We tested the hypothesis that FOXO1 plays a key role in diabetes-impaired angiogenesis and chondrocyte apoptosis." (PMID 37576976, 2023).
diabetes (continued). "For example, L-Methionine (L-Met) regulates FoxO1 by altering the bivalent domain histone methylation marks H3K27me3 and H3K4me3 to increase FoxO1-mediated upregulation of the insulin transcription factor MafA and mitigate type 1 diabetes mellitus in rats." (PMID 37941908, 2023). "We believe that the interaction between FOXO1 and hnRNPK may be involved in the regulation of the expression of a large group of genes and play certain roles in cancer and diabetes." (PMID 36964488, 2023). "Additionally, FoxO1 plays a significant role during protection against oxidative stress through the induction of endogenous antioxidants; moreover, FoxO1 is a master regulator of inflammatory responses during metabolic disorders, such as obesity and diabetes." (PMID 36671037, 2023). "FOXO1 deletion in chondrocytes reversed the effect of diabetes on apoptosis to normal levels." (PMID 37576976, 2023). "We delved deeper into the specifics of MAM protein-protein interactions and discovered key connections between many of the altered MAM proteins in diabetes with several major protein regulators of inflammation, diabetes, and/or DR, specifically IL-1β, NFκBIA, FOXO1, SYVN1, STAT4, MAF, and LGALS3." (PMID 36139394, 2022). "Several of the negative features linked with obesity and diabetes, such as hyperglycaemia and glucose intolerance, are promoted by FoxO1-dependent gene expression." (PMID 36361416, 2022). "Although various studies have highlighted the specific role of FoxO1 in T cell biology, it remains unclear whether FoxO1 presides the regulation of Th17/Treg differentiation in the context of diabetes." (PMID 36463128, 2022). "To verify this hypothesis, we detected the effect of diabetes on FOXO1 expression in pancreatic tissue via Western blot." (PMID 34935260, 2022). "Exenatide could restore systemic Th17/Treg balance via regulating FoxO1 pathway with the progression of diabetes in db/db mice." (PMID 36463128, 2022). "Likewise, the knockout of FoxO1 in the liver decreases the excessive production of glucose, triggered by liver insulin receptor ablation, avoiding diabetes in neonates and fatty liver disease in liver-precise insulin receptor overexpressed mice." (PMID 33804729, 2021). "Several studies investigated the effect of FoxO1 on protecting podocytes from injury in diabetes." (PMID 33859563, 2021). "FoxO1 expression is increased by energy distress (including fasting, calorie reduction, as well as serious diabetes) in skeletal muscles, implying that FoxO1 may facilitate the skeletal muscle’s reaction to altered energy metabolism." (PMID 33804729, 2021). "FoxO1 nuclear compartmentalization and enhancement of its transcriptional activity, together with increases in FA uptake, have been observed in models of long-term diabetes and obesity." (PMID 33727534, 2021). "In the rat heart with STZ-induced diabetes, FoxO1 overactivation was found to shift substrate selection from glucose to fatty acid, induce disarranged oxidative metabolism, mitochondrial dysfunction and cardiomyocyte apoptosis, and ultimately cause cardiac dysfunction." (PMID 34522203, 2021). "In addition, it is generally accepted that poorly controlled diabetes has an adverse effect on periodontal wound healing, which is also partially mediated by FOXO1." (PMID 33860060, 2021). "Diabetes could induce the expression of Sfrp1 and Sfrp4, but FoxO1 knockout slightly reduced Sfrp1 level." (PMID 33609082, 2021). "Our results suggested that 1,25D could promote osteogenesis though down‐regulating FOXO1/FGF23 in diabetes." (PMID 33609082, 2021). "Also, diabetes increased the expression of Foxo1 and Pepck genes and decreased Akt2 gene expression." (PMID 34848753, 2021). "Keratinocyte-specific FoxO1-deficient mice without diabetes exhibited delayed wound healing, but the same mouse model with diabetes had the opposite effect." (PMID 34418600, 2021).